CNTN1 (contactin 1)
Description:
Contactins mediate cell surface interactions during nervous system development. Involved in the formation of paranodal axo-glial junctions in myelinated peripheral nerves and in the signaling between axons and myelinating glial cells via its association with CNTNAP1. Participates in oligodendrocytes generation by acting as a ligand of NOTCH1. Its association with NOTCH1 promotes NOTCH1 activation through the released notch intracellular domain (NICD) and subsequent translocation to the nucleus. Interaction with TNR induces a repulsion of neurons and an inhibition of neurite outgrowth (By similarity).
Synonyms: F3; GP135; CMYO12; CMYP12; MYPCN
Tractability: Antibody: UniProt places it where antibodies can reach, with medium confidence; UniProt predicts a signal peptide or a membrane-spanning region; its Gene Ontology location is reachable by antibodies, with medium confidence. PROTAC: ubiquitination databases record sites on it; its protein half-life has been measured.
Gene: Protein-coding gene on chromosome 12 (40,692,431 to 41,072,415, forward strand). Ensembl gene ENSG00000018236.
Subcellular location: Cell membrane (Isoform 1); Cell membrane (Isoform 2)
Pathways (Reactome):
Developmental Biology: L1CAM interactions; Neurofascin interactions
Signal Transduction: Activated NOTCH1 Transmits Signal to the Nucleus; NOTCH2 Activation and Transmission of Signal to the Nucleus
Gene Ontology:
Molecular function: protein binding; cell-cell adhesion mediator activity; carbohydrate binding
Biological process: axon guidance; brain development; cell adhesion; cell-cell adhesion; central nervous system myelin formation; locomotory behavior; myelination
Cellular component: extracellular exosome; axon; membrane; plasma membrane; glutamatergic synapse; postsynaptic membrane; presynaptic membrane; synapse
Genetic constraint (gnomAD): Loss-of-function variants: 30 observed, 94.39 expected, observed/expected ratio (o/e) 0.32, 90% interval 0.24 to 0.43. The upper end of that interval is the gene's LOEUF score, 0.43, which puts it in group 1 of 6, group 1 being the genes least tolerant of losing a copy. Missense variants: 824 observed, 1,069.7 expected, observed/expected ratio (o/e) 0.77, 90% interval 0.73 to 0.82. Synonymous variants: 346 observed, 370.3 expected, observed/expected ratio (o/e) 0.93, 90% interval 0.86 to 1.02.
Homologues: Orthologues: macaque CNTN1 (99% identical), chimpanzee CNTN1 (98% identical), dog CNTN1 (97% identical), pig CNTN1 (97% identical), guinea pig CNTN1 (96% identical), mouse Cntn1 (95% identical), rabbit CNTN1 (95% identical), rat Cntn1 (93% identical), tropical clawed frog cntn1 (69% identical), zebrafish cntn1b (52% identical), zebrafish cntn1a (35% identical). Paralogues in human: CNTN2 (50% identical), CNTN5 (45% identical), CNTN3 (43% identical), CNTN4 (43% identical), CNTN6 (42% identical), L1CAM (27% identical), CHL1 (26% identical), NRCAM (26% identical), NFASC (25% identical), ROBO1 (21% identical), NEO1 (21% identical), ROBO2 (20% identical), and 24 more.
Diseases named in the same sentence as CNTN1 in open-access papers:
CNTN1 is named in the same sentence as 148 diseases in open-access papers, as found by Europe PMC text mining. Sharing a sentence is not in itself a finding about the gene and the disease. The quoted sentences say what the papers report.
chronic inflammatory demyelinating polyneuropathy (22 papers, 2015 to 2025). "CNTN1, as well as other proteins detected in the paranodal complex of myelinated fibers, have been implicated in chronic inflammatory demyelinating polyradiculoneuropathy (CIDP)." (PMID 33451101, 2021). "The concurrence of anti-contactin 1 (CNTN1) antibody-associated chronic inflammatory demyelinating polyneuropathy (CIDP) and membranous nephropathy (MN) has previously been reported in the literature." (PMID 34675937, 2021). "Antibodies against CNTN1 of IgG4 and IgG1 subclass are present in chronic inflammatory demyelinating polyradiculoneuropathy (CIDP) and were proven to be pathogenic." (PMID 29483905, 2018). "However, its potential as a therapeutic target requires careful evaluation, as immunoglobulin G4 antibodies against Contactin 1 have been linked to chronic inflammatory demyelinating polyneuropathy." (PMID 41299419, 2025). "Similarly, contactin 1 (CNTN1), discovered in 2020, appears to be specifically associated with chronic inflammatory demyelinating polyradiculoneuropathy." (PMID 40500560, 2025). "Anti-NF155 and anti-contactin-1 IgG4 are the most frequently detected antibodies, representing 1 to 20% of chronic inflammatory demyelinating polyradiculoneuropathies, with anti-contactin-associated protein-1 and anti-NF140/186 syndromes occurring less frequently." (PMID 39854764, 2025). "Ideally, if a patient was determined to be CNTN1-positive, they would then be evaluated for chronic inflammatory demyelinating polyradiculoneuropathy." (PMID 40500560, 2025). "Its interaction with neurofascin-155 plays an essential role in propagating pain signals and reduced CNTN1 activity/concentration results in chronic inflammatory demyelinating polyneuropathy and is considered a bona fide marker for pain." (PMID 38239902, 2023). "Anti-CNTN1 antibodies have been found in individuals with chronic inflammatory demyelinating polyneuropathy (CIDP), which raises the possibility that the autoimmune response in MN and the pathophysiology of the underlying neurological lesion are linked." (PMID 37685941, 2023). "CNTN1 was recently identified as a target antigen in MN with chronic inflammatory demyelinating polyneuropathy (CIDP) and autoimmune myositis." (PMID 34899763, 2021). "Anti-contactin 1 autoantibodies, that block/decrease levels of contactin 1, have been described in chronic inflammatory demyelinating polyneuropathy." (PMID 30755720, 2019). "Autoantibodies against contactin-1 were shown to be present in a subset of patients suffering from chronic inflammatory demyelinating polyneuropathy (CIDP), suggesting that contactin-1 is involved in neuromyopathies." (PMID 29249937, 2017). "Auto-antibodies against the paranodal proteins contactin-1 and neurofascin-155 and the nodal protein neurofascin-186 have been detected in subgroups of patients with chronic inflammatory demyelinating polyneuropathy." (PMID 26218529, 2015). "Antibodies against contactin-1, neurofascin and gliomedin have been reported to be present in 2–10% of patients with chronic inflammatory demyelinating polyneuropathy (CIDP) and are supposed to be associated with a typical clinical phenotype of acute onset severe sensorimotor neuropathy and tremor." (PMID 26218529, 2015). "Previous studies have determined the role of CNTN1 in neurogenesis, Alzheimer’s disease, multiple sclerosis, and chronic inflammatory demyelinating polyneuropathy as a neuronal cell adhesion molecule and a component of septate-like junctions between the terminal myelin loops and axolemma." (PMID 33194679, 2020). "Comparison of the clinical characteristics of chronic inflammatory demyelinating polyneuropathy (CIDP) with membranous nephropathy (MN), anti-contactin 1 (CNTN1) antibody-positive AN with MN, and anti-CNTN1 antibody-associated AN." (PMID 34675937, 2021).
chronic inflammatory demyelinating polyneuropathy (continued). "Nevertheless, it is quite unusual for individuals to simultaneously manifest both chronic inflammatory demyelinating polyneuropathy (CIDP) and MN along with the presence of positive anti-contactin-1 (CNTN1) antibodies." (PMID 40502862, 2025). "Chronic inflammatory demyelinating polyradiculoneuropathy (CIDP) is a IgG4-AID, and one of the possible antigens in this disorder is CNTN1." (PMID 38433835, 2024).
neuropathy (18 papers, 2019 to 2025). A disorder affecting the nervous system that manifests with pain, tingling, numbness, and/or muscle weakness. "Neuropathy workup was integrated by anti‐neurofascin 155, anti‐panneurofascin, anti‐contactin 1 (CNTN1), and anti‐contactin associated protein 1 (CASPR1) antibodies and next‐generation sequencing for CMT, which were negative." (PMID 40685796, 2025). "Previous case reports have suggested an association between patients with anti-contactin-1 (CNTN1)-mediated neuropathies and MGN." (PMID 36893151, 2023). "In a previously reported case of anti-contactin-1-associated membranous glomerulonephritis, nephrotic syndrome was alleviated after hormone therapy, whereas neuropathy rapidly worsened, resulting in axonal involvement." (PMID 34675937, 2021). "Structural changes of the paranodal region are therefore supposed to be involved in the pathogenicity of anti-CNTN1-associated neuropathy." (PMID 30953561, 2019). "In this study, we detected conduction blocks and motor deficits in rats intraneurally injected with IgG of patients with anti-CNTN1-associated neuropathy." (PMID 30953561, 2019). "This supports the notion of anti-contactin-1-associated neuropathy as a paranodopathy with the nodes of Ranvier as the site of pathogenesis." (PMID 30953561, 2019). "Several studies demonstrated disruption of the paranodes in patients with anti-CNTN1-associated neuropathy." (PMID 30953561, 2019). "A primary autoimmune membranous nephropathy can be associated with anti-CNTN1-related neuropathy." (PMID 39050350, 2024). "Thus a total of 15 patients, summarised here had a CNTN1 antibody-associated neuropathy and nephropathy." (PMID 36893151, 2023). "Patients with acute-onset contactin-1-associated neuropathy may experience a switch in predominant antibody subclass from IgG3 to IgG4, but further longitudinal studies are required for confirmation." (PMID 34675937, 2021). "In another study, severe destruction of paranodal and nodal architecture was detected in the peripheral nerves of patients with CNTN-1-associated neuropathy, with a loss of CASPR or the nerve excitation immune response and an increase in internode length occurring at certain nodes." (PMID 34675937, 2021). "Of interest, a recent study showed that complement deposition may contribute to the pathophysiology of anti-CNTN1-associated neuropathy, particularly in patients with a predominance of the IgG3 subclass." (PMID 31753915, 2020). "Purified IgG of three patients with anti-CNTN1-associated neuropathy was used for the experiments." (PMID 30953561, 2019). "Further indicators of a pathogenic role of paranodal autoantibodies are the destruction of paranodal architecture detectable in patients with anti-CNTN1 associated neuropathy, the excellent therapeutic response to rituximab and the uniform clinical phenotype of the patients." (PMID 30953561, 2019). "Different pathomechanisms may contribute to the clinical picture of anti-CNTN1-associated neuropathy, possible at different stages of disease and should be taken into account in therapeutic approaches." (PMID 30953561, 2019). "A study highlighted that patients with anti-CNTN1 antibodies often present with aggressive neuropathy and poor response to standard therapies." (PMID 40502862, 2025). "Case 2 was complicated with nephrotic syndrome, which improved in parallel with neuropathy and CNTN1-IgG status." (PMID 40995362, 2025). "Anti‐CNTN1 and anti‐Caspr1 antibodies are often found in older individuals with aggressive neuropathy and cranial nerve involvement." (PMID 40637635, 2025). "As far as we know, there has been only one case of anti-CNTN1 AN with thymoma, which was detected within six months of neuropathy onset." (PMID 40995362, 2025). "We have recently shown that serum levels of CNTN1 protein (sCNTN1) are lower in antibody-positive neuropathy patients compared with seronegative and healthy controls." (PMID 36893151, 2023).
neuropathy (continued). "CNTN1 antibody titres were high prior to immunosuppressive treatment, and lower in remission of both neuropathy and nephropathy (p = 0.001)." (PMID 36893151, 2023). "In summary, the improvement of neuropathy and renal disease following immunotherapy highlights the utility of CNTN1 antibodies in the identification of a clinically reversible disorder." (PMID 36893151, 2023). "CNTN1 seropositive patients were largely resistant to first-line neuropathy treatments but achieved a good outcome with escalation therapies." (PMID 36893151, 2023). "Further, locally available sera from patients found to have CNTN1 antibodies, neuropathy and nephrotic syndrome were pre-adsorbed with recombinant CNTN1 protein and re-applied to live CBA or neuronal co-cultures." (PMID 36893151, 2023). "None of the healthy or pathologic controls tested, including patients affected by other neuropathies, showed reactivity against Nfasc155, CNTN1, or Caspr1." (PMID 31753915, 2020). "However, some reports have noted more severe or rapidly progressive neuropathy in anti-CNTN1-positive patients." (PMID 40502862, 2025). "Thus, patients with MGN and signs of neuropathy should rather be screened for contactin-1 than Caspr-1 antibodies." (PMID 39434877, 2024). "Summary of patients with neuropathy, nephrotic syndrome and CNTN1 antibodies." (PMID 36893151, 2023). "We therefore hypothesised that acute exposure of anti-CNTN1 IgG containing IgG3 may induce an acute neuropathy with reversible conduction failure, corresponding to the original concept of paranodopathy." (PMID 30953561, 2019). "Antigen‐specific efficacy varied: NF186 neuropathy resolved completely, while IgG4‐dominant paranodal cases (NF155/CNTN1) partially recovered, prompting sequential B‐cell‐targeted strategies." (PMID 40637635, 2025). "Efgartigimod induced rapid functional improvement in four patients with autoimmune nodopathy, achieving complete remission in anti‐NF186 IgG3+ neuropathy and partial recovery in IgG4‐dominant paranodal subtypes (anti‐NF155/CNTN1+)." (PMID 40637635, 2025). "Four of 295 (1.4%) patients with isolated membranous nephropathy without neuropathy had anti‐CNTN1 IgG4 antibodies, suggesting that contactin was expressed on the podocyte, glomerular loop, or glomerular basal membrane." (PMID 38980226, 2024). "PLA2R antibody testing was performed where possible, and found to be negative in these four, and 10/15 patients with CNTN1 antibodies, nephrotic syndrome and a neuropathy (14/19 in total)—the remaining sera unavailable for further testing." (PMID 36893151, 2023). "In a late case report of a 43-year-old male with CIDP who developed MN with nephrotic syndrome one year after being diagnosed with neuropathy, IgG4 anti-CNTN1 but not anti-PLA2R antibody was detected." (PMID 33808418, 2021). "A previous report found non-concordant presentation of nephrotic syndrome and neuropathy in a patient with anti-CNTN1 antibodies—separated by a year, implying that some patients may further develop the combined neuro-renal syndrome at a later stage." (PMID 36893151, 2023). "We also tested for CNTN1 antibodies in 295 patients with idiopathic MGN without neuropathy." (PMID 36893151, 2023).
lung carcinoma (14 papers, 2009 to 2024). "CNTN1 facilitates lung cancer metastasis and associates with poor prognosis in patients with lung, esophageal and oral squamous cell carcinomas, and hepatocellular carcinoma." (PMID 33578925, 2021). "initially found CNTN1 to be associated with lung cancer, the relationship between CNTN1 and cancer has been studied in different cancer types, along with related molecules and signal transduction pathways." (PMID 33194679, 2020). "CNTN1, a protein encoded by CNTN1, promoted lung cancer invasive and metastasis." (PMID 29158875, 2017). "For example, knockdown of CNTN1 has been shown to reduce the invasion of lung cancer, oral squamous cell carcinoma, and thyroid cancer cells, while overexpression increased lung metastasis in a mouse model of prostate cancer." (PMID 39595172, 2024). "Through activation of the phosphatidylinositol 3-kinase (PI3K)/AKT signaling pathway, CNTN-1 promotes cisplatin resistance in cisplatin-resistant lung cancer cells and resistant cells." (PMID 34659414, 2021). "The expression of CNTN1 is correlated with drug resistance, and depletion of CNTN1 reverses the drug sensitivity in lung cancer cell lines." (PMID 33194679, 2020). "This enhanced chemoresistance of lung cancer cells induced by CNTN1 overexpression was also found to be attributable to PI3K/AKT activated EMT enhancement." (PMID 32752094, 2020). "Intriguingly, CNTN1 is also important in promoting chemo-resistant properties in lung cancer cells via induction of EMT." (PMID 32752094, 2020). "For instance, while the VEGFC/Flt4 pathway unregulated CNTN1 expression in lung cancer, CNTN1 upregulation in prostate cancer is an outcome of the conversion of non-CSC PC cells to PCSC and CNTN1 in turn contributes to PCSC-derived metastasis." (PMID 32752094, 2020). "CNTN1 was found to mediate tumor invasion and metastasis in lung cancer through activation of RhoA, which regulates the actin cytoskeleton and cell motility." (PMID 29673312, 2018). "The finding that CNTN1 mediates metastasis and invasion in lung cancer prompted investigation into the capacity of CNTN1 to drive invasion and metastasis of other tumors." (PMID 29673312, 2018). "We report here that knockdown of contactin-1 in A549 lung cancer cells reduced A549 cell invasion and the cell's ability to grow in soft agar without affecting cell proliferation." (PMID 23724143, 2013). "Nonetheless, our research is consistent with publications showing that CNTN-1 promotes lung cancer metastasis and that E-cadherin is a major contributor to the invasion and metastasis of epithelium-origin cancers." (PMID 23724143, 2013). "Collectively, we provide evidence that contactin-1 plays a role in the downregulation of E-cadherin in lung cancer and that AKT activation contributes to this process." (PMID 23724143, 2013). "To further investigate CNTN-1-mediated lung cancer metastasis, we have knocked-down CNTN-1 in A549 cells." (PMID 23724143, 2013). "To further determine the relationship between CNTN-1 and E-cadherin, we have examined 63 primary lung carcinomas." (PMID 23724143, 2013). "Taken together, our investigation supports the concept that CNTN-1 facilitates lung cancer progression/metastasis in part via downregulation of E-cadherin." (PMID 23724143, 2013). "This concept is based on our study of the knockdown of CNTN-1 in A459 cells as well as the examination of CNTN-1 and E-cadherin in 63 primary lung carcinomas." (PMID 23724143, 2013). "CNTN-1 was detected in primary lung cancer and knockdown of CNTN-1 in lung cancer cells specifically inhibited their metastasis but not the formation of local xenograft tumours in immunocompromised mice." (PMID 23724143, 2013). "Reports have demonstrated CNTN1 to be upregulated in many types of cancer such as lung cancer, oesophageal squamous cell carcinomas, gastric cancer, thyroid cancer, prostate cancer and hepatocellular carcinoma, suggesting its contribution to carcinoma progression, invasion, and metastasis." (PMID 39655212, 2024).